CRP (C-reactive protein)
Diseases named in the same sentence as CRP in open-access papers (continued):
Sharing a sentence is not in itself a finding about the gene and the disease.
depression (continued). "The high-sensitivity test for CRP, called low-reactive protein (LRP, L-CRP, or hs-CRP), more accurately measures very low levels of CRP, and static sampling of CRP has been widely used in clinical studies to predict diseases, such as cancer and depression." (PMID 36860788, 2023). "Inflammatory markers such as interleukin-6 (IL-6) and C-reactive protein (CRP), synthesized by adipocytes, are related to depression-related symptoms." (PMID 37621933, 2023). "In summary, we see a retained effect of adiposity on depression with these more granular phenotypes and an attenuating effect of CRP, as with BMI but more subtly." (PMID 37710313, 2023). "Here, one study on infliximab therapy in depressed patients found that treatment response based on the Hamilton Depression Rating Scale 17 (HAM-D-17) only showed improvement in patients with hs-CRP > 5 mg/L." (PMID 37763150, 2023). "It was found patients with depression and anxiety have higher inflammation than general population, measured as proinflammatory cytokines and CRP." (PMID 37344456, 2023). "We found mtDNA × CRP interactions differed in male, female and total subjects with anxiety or depression." (PMID 37344456, 2023). "The post-surgical decrease in CRP mediated the relationship between post-surgery reduction of adiposity (visceral fat) and post-surgery increase of cortical thickness in depression-related cortical regions." (PMID 37484955, 2023). "Our study results suggested the contribution of mtDNA × CRP interactions in the development of anxiety and depression." (PMID 37344456, 2023). "The present study investigated the relationship between hs-CRP levels and depression scores in middle-aged and older adults using longitudinal analysis in a nationally representative cohort." (PMID 36860788, 2023). "However, it is uncertain whether these associations reflect causal effects of serum CRP, causality in the reverse direction (i.e. depression and anxiety causing increased serum CRP levels), or confounding due to common causes of elevated serum CRP and anxiety and depression." (PMID 37217205, 2023). "Magnesium deficiency is associated with higher levels of C-reactive protein (CRP) and its precursors, such as interleukin (IL)-6 and IL-1, both of which are positively associated with the incidence and severity of depression." (PMID 37049401, 2023). "The samples were analysed for inflammatory biomarkers (C-reactive protein (CRP) and cytokines) and vitamin C content and were related to scales of depression and anxiety." (PMID 37107316, 2023). "Some studies also found an inverse connection between CRP and vitamin C levels in special populations such as pregnant women with depression and anxiety and patients with septic cardiomyopathy." (PMID 38024382, 2023). "In a large, case-control study of depression in the UK Biobank, low-grade inflammation was identified in 21% of patients (defined as serum CRP > 3 mg/L)." (PMID 37111100, 2023). "About a quarter of patients with depression likely display evidence of low-grade inflammation, with over half of patients having mildly elevated C-Reactive Protein levels." (PMID 37217917, 2023). "And a large number of studies have shown that depressed patients with depression have C-reactive protein (CRP), prostaglandins, and other arachidonic acid derivatives, as well as IL-6, IL-1β and TNF-α were significantly increased." (PMID 37492068, 2023). "rs2228145 has been associated with decreased IL-6-induced C-reactive protein (CRP) levels and depression severity." (PMID 38275640, 2023). "A meta-analysis including 27 studies with 84,093 participants showed that CRP levels were moderately elevated in BD patients during depression and euthymia, and more significantly increased during mania." (PMID 37340368, 2023). "Our analysis shows that the effects of CRP on depression remain significant after controlling for serum magnesium, and the effects of serum magnesium diminished after controlling for CRP." (PMID 37049401, 2023).
depression (continued). "Participants’ sociodemographic characteristics differed significantly for age, income, smoking status, physical activity status, kidney disease, and CRP levels when depression status was treated as a binary variable." (PMID 37049401, 2023). "Third, CRP was collected in two waves, which limits our ability to assess the dynamic interaction between CRP and depression." (PMID 36860788, 2023). "Evidence from a longitudinal Australian older-adult cohort showed a positive association between SFA intakes and depressive symptoms mediated by C-reactive protein, suggesting a critical role of inflammation on the onset of depression." (PMID 36771380, 2023). "Cytokines, such as interferon-γ (IFNγ), C-reactive protein (CRP) and IL-6, increase with chronic stress, correlate with the severity of depression and predict cognitive changes in depression." (PMID 37836393, 2023). "Increased inflammatory cytokines in the brain and in serum, such as CRP, and soluble cell-adhesion molecules IL-6, IL-1β, TNF-α and NF-κB, would be involved in the susceptibility to depression in stressed obese mice." (PMID 37836393, 2023). "Third, understanding the link between inflammation and TRD will lead to new treatments for managing depression, as measuring the expression levels of CRP and other cytokines allows for individualizing treatment plans for patients." (PMID 36648973, 2023). "With the recent advent of Mendelian randomization studies, further discrepancies have become apparent in depression research, where have challenges arisen in disentangling the protective effects of CRP from its risks." (PMID 36831896, 2023). "The clinical study was based on the outcomes to demonstrate the relationship between TRD and inflammation in human models of depression by measuring inflammatory biomarkers CRP, Interleukin-6 (IL-6) and TNF-α and stress markers (corticosterone)." (PMID 36648973, 2023). "More overweight, younger, higher levels of CRP, IL-1rα, and white-cell counts in patients with depression." (PMID 38299049, 2023). "Proinflammatory proteins that likely predict multiple aspects of depression include CRP and fibrinogen." (PMID 35924730, 2023). "Of the proteins assessed, IL-6 and CRP were the only proteins that accounted for a significant indirect effect of adiposity on depression symptoms (IL-6: β = .034, bootstrapped 95% CI [.015.070]; CRP: β = .046, bootstrapped 95% CI [.008.086])." (PMID 37393056, 2023). "We observed large effect sizes of CRP (v. other proxy immunometabolism markers) predicting depression components in the within-person temporal networks (d = 1.072–2.112)." (PMID 35924730, 2023). "We also concluded that increased levels of inflammatory markers (CRP, IL-6, PCT, D-dimer, and serum ferritin) were associated with increased prevalence of psychiatric manifestations like depression." (PMID 37621784, 2023). "In perspective, patients with high baseline C-reactive protein (CRP) displayed more aggressive symptoms of depression, including little physical activity, bad mood, suicidality, and cognitive deficits." (PMID 37375795, 2023). "Magnesium and zinc with their anti-inflammatory properties can down-regulate CRP, and consequently can reduce depression." (PMID 37386551, 2023). "Serum levels of C-reactive protein (CRP) and interleukin-6 (IL-6) have been associated with anxiety and depression in cross-sectional and Mendelian randomisation studies, but results regarding the effect size and direction have been mixed." (PMID 37217205, 2023). "Among those positively associated with depression are C-reactive protein, IL-6 and TNF-α while markers negatively associated with depression include KYNA, KYNA/3HK ratio, KYNA/QUIN ratio and BDNF." (PMID 37457896, 2023). "Do post-surgery changes in CRP mediate the relationship between post-surgery changes in visceral fat and cortical thickness in the depression regions?" (PMID 37484955, 2023).
depression (continued). "There is evidence that people with major depressive disorder have higher levels of CRP and other proinflammatory biomarkers." (PMID 37860004, 2023). "Participants who slept more than 6 h per night showed greater CRP levels when compared to women who slept less than 6 h after controlling for body mass index, depression, and PTSD severity." (PMID 37081449, 2023). "A double-blind, placebo-controlled, randomized clinical trial in treatment resistant depression found that infusions of infliximab significantly reduced scores on the HAM-D at week 12 in patients with a baseline CRP concentration greater than 5 mg/L." (PMID 37252156, 2023). "In a randomized trial of participants with treatment-resistant depression, the TNFα inhibitor infliximab reduces depression scores, but only in the subpopulation of patients displaying elevation of the inflammatory marker C-reactive protein." (PMID 37706039, 2023). "An increase in pro-inflammatory cytokines, namely IL-6, IL-1β, tumor necrosis factor α, and C-reactive protein (CRP), participate actively in the development of depression." (PMID 37139495, 2023). "Third, regarding the effects of control variables on CRP and depression, we found that most control variables were significantly correlated with depression and CRP in 2011 and 2015 (ps < 0.05, ranging from 0.00 to 0.04)." (PMID 36860788, 2023). "We have applied a range of methods that provide causal estimates in a methodologically robust fashion, that suggest that the effect of CRP on depression outcomes is likely attributable to the influence of BMI." (PMID 37710313, 2023). "AGP1 is increased in plasma during the acute phase of depression, in which it positively correlates with high concentrations of IL-6 and C-reactive protein (CRP)." (PMID 38049858, 2023). "In depression, recent work has indicated a higher CRP in 102 individuals with TRD compared with treatment-responsive patients and controls." (PMID 37710313, 2023). "The clinical samples provided a dose–response relationship, indicating that higher IL-6 and CRP predicted the follow-up progress of depression." (PMID 36846218, 2023). "Individuals with symptoms of anxiety and with symptoms of anxiety and depression had higher CRP levels relative to the control group." (PMID 38111613, 2023). "Psychological and physiological factors are related to anxiety, loneliness and depression, and increased levels of pro-inflammatory biomarkers (IL-6 and CRP) in patients that perceive themselves as isolated." (PMID 37510818, 2023). "Our mediation analyses suggested that the effect of CRP on severity of depression was partly mediated by BMI." (PMID 37710313, 2023). "There was moderate evidence for a positive correlation between log-normalized CRP and both depression severity and reduced activity." (PMID 36831896, 2023). "A significant increase (p < 0.001) in the levels of CRP was observed in prostate and breast cancer patients, which was further enhanced with accompanying depression." (PMID 37153524, 2023). "Alternatively, Akkasheh and colleagues reported decreases in C-reactive protein and Beck Depression scores after supplementing for 8 weeks with L. acidophilus, L. casei and B. bifidum (6 × 109 CFU/day)." (PMID 37720373, 2023). "In contrast, correlations with factors such as depression, peripheral vascular disease, and the Horvath and PhenoAge epigenetic clock, for which EIS exhibited stronger associations than CRP, were relatively similar among cEIS, EIS, and the random set." (PMID 37139638, 2023). "In the present study, we found several significant mtDNA × CRP interactions for anxiety and depression respectively." (PMID 37344456, 2023). "We observed a positive correlation of CRP values with a reduction of depression severity assessed by BDI after the antidepressant treatment (r = 0.5; p = 0.0169)." (PMID 38002663, 2023).
depression (continued). "Those with baseline CRP values of greater than 8mgI-1 showed a significant decrease in Hamilton Depression Rating Scale scores with Sirukumab as an adjunct treatment." (PMID 38299049, 2023). "Our study suggests the important interaction effects of mitochondrial function and CRP on the risks of anxiety and depression." (PMID 37344456, 2023). "The Younger 2013 study also excluded patients with C-reactive protein level >2 mg/dL, significant psychiatric distress, or Revised Beck Depression Inventory (BDI-II) score >29." (PMID 37206027, 2023). "A low body mass index and high C-reactive protein levels were associated with higher VAS scores; a high estradiol level was a factor for anxiety/depression aggravation (<0.05)." (PMID 36983400, 2023). "In this paper, we aim to estimate the causal contributions of CRP and BMI on TRD and other depression phenotypes using a combination of UVMR, MVMR and causal mediation analyses." (PMID 37710313, 2023). "Patients of depression showed evidence of low-grade inflammation (>3 mg/L) and mildly elevated CRP levels (>1 mg/L)." (PMID 37344456, 2023). "Missing information on variables including PIR (n = 420), depression (n = 56), drinking (n = 302), BMI (n = 78), education level (n = 2), smoking (n = 2), and CRP (n = 1) were deleted." (PMID 38170097, 2023). "The TNFα inhibitor infliximab reduces depression scores, but only in a subpopulation of individuals with higher levels of the inflammatory marker C-reactive protein." (PMID 37706039, 2023). "Some studies found patients with depression to have increased levels of C reactive protein (CRP), an important inflammatory marker." (PMID 36978923, 2023). "Against this background, we investigated the relationship of peripheral tryptophan catabolites with depression in a population-based sample with n = 3,389 participants (with fasting status ≥ 8 h and C-reactive protein < 10 mg/L)." (PMID 36631760, 2023). "It is possible that an elevated level of CRP is a key contributor to treatment-resistant depression in at least some BDD patients." (PMID 37181328, 2023). "CRP protein, on the other hand, is considered a systemic inflammation biomarker, which is commonly elevated in patients suffering from depression." (PMID 36769269, 2023). "The results indicated that compared to controls, patients typically have higher inflammatory biomarkers (i.e., TNF-alpha, TNFR1, TNFR2, CRP, IL-1ra) and worse fatigue, depression, and sleep (ps < 0.05)." (PMID 37444517, 2023). "The mean value of high-sensitivity CRP concentration was significantly higher in patients who had treatment-resistant depression, compared to the treatment-responsive patients (61.0 ± 97.0 mg/L vs. 11.08 ± 7.7 mg/L; p = 0.031)." (PMID 36648973, 2023). "A randomized, double-blind clinical trial was conducted to study the effect of probiotics on symptoms of depression, metabolic profiles, and serum CRP in patients with major depressive disorder." (PMID 37692658, 2023). "The results also indicated that both patients and controls with higher levels of circulating CRP than other participants, on average, reported worse depression." (PMID 37444517, 2023). "Mediation analyses revealed that the relationships between the surgery-related changes in visceral fat and cortical thickness in depression-related regions are mediated by changes in CRP (ab=-.027, SE=.012, 95% CI [-.054, -,006])." (PMID 37484955, 2023). "The interaction between mtDNA and CRP is discussed as a promising new biomarker for diagnosis and treatment effects in anxiety and depression." (PMID 37344456, 2023). "We estimated the effects of log-normalized CRP on multidimensional self-reported interoception, fatigue, and overall depression severity, after adjusting for relevant covariates." (PMID 36831896, 2023). "Laboratory results, including neutrophil lymphocyte ratio (NLR) upon admission, higher interleukin-6 (IL-6), and higher C-reactive protein (CRP), were associated with depression." (PMID 37027455, 2023).
depression (continued). "Meta-analyses have found increased C-reactive protein (CRP) and interleukin-6 (IL-6) in CVD patients, both of which are associated with higher risk of depression." (PMID 37009113, 2023). "For instance, the MINDEP study selecting MDD patients with C-Reactive Protein (CRP)>1 mg/l showed a positive effect of minocycline augmentation on depression in post-hoc analyses for patients with elevated inflammation [CRP≥3 mg/l]." (PMID 36655056, 2023). "Compared to hypertensive individuals without type 2 diabetes, hypertensive individuals with type 2 diabetes had higher body mass index, age, CRP levels and scores on the Anhedonia subscale of the Beck Depression Inventory (items 4, 12 and 21)." (PMID 35023283, 2022). "Another cross-sectional study, including 764 (336 male and 579 female) individuals assessed through the Short Zung Self Rating Depression Scale (SZRDS), showed a positive correlation between hs-CRP levels and depression mood, exclusively in men." (PMID 35163538, 2022). "A recent metanalysis reported an increase in systemic pro-inflammatory cytokines, IL-1, IL-6, TNF-alpha and C-reactive protein (CRP) in depression patients." (PMID 35323251, 2022). "It has been shown that the inflammatory factors IL-1β, IL-6, TNF, and C-reactive protein (CRP) in peripheral blood are reliable biomarkers for patients with depression." (PMID 36186850, 2022). "Cortisol levels are related to both severity of depression and anhedonia, whereas the levels of IL-6 and CRP are merely related to anhedonia, which suggests that patients with anhedonic MDD have unique neuroendocrine-immune characteristics." (PMID 36090246, 2022). "We further assessed the mediation effect of CRP on the association of the DII and depression, using structural equation modeling." (PMID 35565951, 2022). "Variants associated with increased risk for depression were also associated with increased risk of CAD, and higher TG, LDL and CRP levels, while there were an opposite or mixed pattern of effect direction for the other traits." (PMID 35560157, 2022). "These comparisons appear to indicate that elevated levels of the inflammatory marker, CRP, are specifically tied to neurovegetative features of depression." (PMID 35361785, 2022). "In the patients in the participants with higher depression rating scores group, sedimentation rate, leukocyte count, and CRP values were found to be high." (PMID 36326335, 2022). "In adults with JIA, cognitive decline was directly associated with average inflammatory activity measured based on C-reactive protein and with depression." (PMID 35885032, 2022). "In subjects free of apathy and depression at baseline, subjects in the highest CRP-tertile at baseline had significantly more increase in depressive symptoms but not in apathy symptoms during follow-up." (PMID 36572691, 2022). "In a study of refractory depression, infliximab, a TNF-α inhibitor, did not have generalizable benefit in the treatment of refractory depression, but did result in clinical benefits in patients with elevated CRP at baseline." (PMID 36704001, 2022). "RA activity has been shown to correlate with high plasma levels of C-reactive protein (CRP), as well as depression severity in this subgroup of patients." (PMID 36422176, 2022). "C-reactive protein (CRP) is one of the members of acute phase protein which is widely used for the diagnosis of depression in many previous studies." (PMID 36217471, 2022). "Increases in psychological distress from before to during the pandemic were also observed for individuals with high CRP for loneliness, and multiple ACEs and higher hair cortisol levels for depression." (PMID 36198766, 2022). "Many of the most robustly validated circulating molecular biomarkers implicated in depression are cytokines involved in the pathway for general inflammation (e.g., IL-6, TNF-α, C-reactive protein (CRP), and interferons)." (PMID 36075922, 2022).